ENPEP (glutamyl aminopeptidase)
Diseases named in the same sentence as ENPEP in open-access papers (continued):
Sharing a sentence is not in itself a finding about the gene and the disease.
hyperthyroidism (1 paper, 2017). Overactivity of the thyroid gland resulting in overproduction of thyroid hormone and increased metabolic rate. "We provide here first evidence that hyperthyroidism leads to decreased expression of PITX2 and ENPEP in the atrial chambers." (PMID 29194452, 2017).
hypertriglyceridemia (1 paper, 2023). A laboratory test result indicating elevated triglyceride concentration in the blood. "However, PPARα modulators that are used as triglyceride-lowering agents induce hepatic expression of ENPEP and ENPEP peptidase protects against hypertriglyceridemia." (PMID 37628732, 2023).
myelodysplastic syndrome (1 paper, 2025). A clonal hematopoietic disorder characterized by dysplasia and ineffective hematopoiesis in one or more of the hematopoietic cell lines. "DisGeNET data reveal associations between myelodysplastic syndrome and the genes CD36, DAB2, ENPEP, and TIMP1." (PMID 40565366, 2025).
renal dysfunction (1 paper, 2017). "The aim of this work was to investigate if the content of glutamyl aminopeptidase (GluAp) in microvesicular and exosomal fractions of urine is related with renal dysfunction in cisplatin-treated rats." (PMID 28399178, 2017).
stomach cancer (1 paper, 2020). "We observed an increased expression of ACE2, DPP4, ANPEP, and ENPEP in renal tumor data available on TCGA followed by gastrointestinal cancers such as colorectal, pancreatic, and stomach cancer." (PMID 33330620, 2020).
infection (34 papers, 2005 to 2025). The state of being infected such as from the introduction of a foreign agent such as serum, vaccine, antigenic substance or organism. "Other proteinases that facilitate virus entry, such as alanyl-aminopeptidase (ANPEP), glutamyl aminopeptidase (ENPEP), and transmembrane serine protease 2 (TMPRSS2), may also aid in the infection of lung cells." (PMID 39591123, 2024).
tumor (20 papers, 2013 to 2025). "Gross pathological examination showed that the size of the tumor mass was about 14 × 10 × 6 cm.Mutations were observed in ENPEP (4q25), ZCCHC11, RREB1 (6p24.3), CKAP4 (12q23.3), and other genes were detected by whole exome sequencing." (PMID 36805679, 2023). "Among the microRNA binding sites observed, miR-125b has been shown to act as a tumor suppressor in breast tumorigenesis by directly targeting the ENPEP gene." (PMID 29900035, 2017). "In its tumor-suppressive functions, miR-125b has been reported to target ENPEP, CK2-α, CCNJ, MEGF9 or the proto-oncogene ETS1." (PMID 25633049, 2015). "miR-125b was found to perform its tumor suppressor function via the direct targeting of the 3’-UTRs of ENPEP, CK2-α, CCNJ, and MEGF9 mRNAs." (PMID 24098452, 2013). "Among the down-regulated miRNAs, miR-125b-5p was favoured to have tumour suppressor roles by targeting ENPEP gene, where enforced expression in MCF-7 cells reduced cell proliferation and anchorage-independent growth by positive regulation in breast tumorigenesis." (PMID 28717596, 2017). "The expression levels of the genes CD36, CXCL14, DAB2, MARCKS, ENPEP, and TIMP1 in normal, tumor, and metastatic tissues were analyzed using various statistical methods." (PMID 40565366, 2025). "ENPEP mRNA levels were higher in low grade CCRCCs than in high grade tumours, however, this result was not statistically significant (Mann–Whitney test p = 0.322)." (PMID 24885240, 2014). "Organ confined CCRCCs showed similar ENPEP mRNA levels to non-organ confined tumours (p = 0.856)." (PMID 24885240, 2014). "The differences between tumor and metastatic tissues were gene-specific; for instance, no significant changes were observed in some genes, such as CD36 and ENPEP (p = 0.42), whereas significant changes were detected in others, such as MARCKS (p = 5.40 × 10−7)." (PMID 40565366, 2025).
cancer (7 papers, 2013 to 2025). A tumor composed of atypical neoplastic, often pleomorphic cells that invade other tissues. "We next investigated the effect of ENPEP mutation on prognosis of ICIs treatment in a pan‐cancer cohort (Miao cohort) which was comprised of 249 patients, with more than 10 types of tumors." (PMID 34862755, 2022). "We first investigated the mutation rate of ENPEP in 25 cancers in the TCGA databases." (PMID 34862755, 2022). "Strong connections to angiogenesis and other processes related to vascular development imply roles for ENPEP in pathological states such as cancer, cardiovascular disease, and tissue remodeling." (PMID 39661628, 2024). "In summary, our results indicated that ENPEP expression and ENPEP mutation is associated with ICI treatment efficacy in pan‐cancers." (PMID 34862755, 2022). "Consistently, we found ENPEP expression is positively correlated with M2 macrophage scores in most cancer (64%)." (PMID 34862755, 2022). "ENPEP mutations, and therefore lower ENPEP expression, were associated with longer OS of ICI‐treated patients in pan‐cancers." (PMID 34862755, 2022). "DPP4, ANPEP, and ENPEP RNA expression were also elevated in renal tumors compared to other cancer tissues." (PMID 33330620, 2020). "Higher APA mRNA levels were observed in patients in advanced stages of cancer, suggesting a correlation between ENPEP and degree of malignancy." (PMID 28177885, 2017). "This study examines the effects the expression of the gene ENPEP may have on predicting performance of immune checkpoint inhibitors in treating various types of cancers." (PMID 34862755, 2022). "In this study, we did landscape profiling of CoV receptors (viz ACE2, TMPRSS2, ANPEP, ENPEP, and DPP4) in various normal and cancer cells." (PMID 33330620, 2020). "Based on the Whole‐exome sequencing (WES) data from TCGA database, we found that ENPEP expression is not correlated with TMB in most cancers (16%)." (PMID 34862755, 2022). "The relevance of ENPEP, CK2-α, CCNJ, and MEGF9 proteins in cancer is gradually being revealed." (PMID 24098452, 2013). "Accordingly, ENPEP expression is absent in normal cells and is overexpressed in cancer cell lines compared with normal cells of mammary origin (data not shown)." (PMID 24098452, 2013).
ENPEP also shares sentences with these, for which no sentence is quoted: HIV-1 infection (10 papers); essential hypertension (4); viral infection (4); influenza (2); lymphoma (2); -dependent (1); abscess (1); AIDS (1); Alzheimer disease (1); aortic valve disease (1); bacterial infections (1); benign tumors (1); cardiovascular disease (1); co-infection (1); dementia (1); diabetes (1); dyslipidemia (1); fibromyalgia (1); glioma (1); hyperaldosteronism (1); Hypercholesterolemia (1); hypothyroidism (1); insulinoma (1); latent infection (1); lung adenocarcinoma (1); measles (1); myocardial infarction (1); neuroblastoma (1); pancreatitis (1); papilloma (1).
A further 4 diseases each share a sentence with ENPEP in 1 paper.